POSTN (periostin)
Diseases named in the same sentence as POSTN in open-access papers (continued):
Sharing a sentence is not in itself a finding about the gene and the disease.
cancer (continued). "Pro-fibrotic fibroblasts were transcriptionally similar to cancer associated fibroblasts and expressed high levels of collagens and periostin (POSTN), thymocyte differentiation antigen 1 (THY-1), and endothelin receptor A (EDNRA) predicted to be driven by a RUNX1 gene regulatory network." (PMID 36747878, 2023). "Periostin is associated with several diseases, including cancers." (PMID 37353600, 2023). "However, the knockout of the POSTN gene caused the PSC-conditioned media to completely lose its cancer migration/invasion-promoting effects in response to the stimulation of CTHRC1." (PMID 37444482, 2023). "Furthermore, we exprlored the expression of marker genes (PDPN, THY1, PDGFRB, PDGFRA,and POSTN) for cancer-associated fibroblasts (CAFs) in different cell types, and found that all marker genes were highly expressed in fibroblasts." (PMID 36973787, 2023). "POSTN expression was mainly observed in endothelial cells and cancer‐associated fibroblasts (CAFs)." (PMID 36691359, 2023). "Overexpression of POSTN have been implicated in several types of human cancers." (PMID 35831854, 2022). "Finally, we will discuss approaches that target periostin or related signaling pathways to develop novel cancer diagnostic and therapeutic strategies." (PMID 36224629, 2022). "In addition, the interplay between cancer cells and peritumoral stromal cells was shown to cause carboplatin and paclitaxel chemoresistance due to high POSTN expression." (PMID 36550569, 2022). "Furthermore, chemotherapy upregulated cancer-specific variants of POSTN and application of a blocking antibody specifically targeting those variants overcame chemoresistance as well as halted disease progression in the absence of toxic effects." (PMID 35268340, 2022). "As advanced studies with periostin, it has been known to play a great role not only in wound repair, heart morphogenesis, metastases, and cancers, but also in eosinophil-associated with inflammatory disease including upper airways and lower airways, such as bronchial asthma and ECRS." (PMID 32954441, 2021). "Whereas patients with LC-IPF have few treatment options because of the risk of IPF progression following cancer treatment, a periostin-targeted therapeutic agent for LC-IPF may be clinically beneficial for both IPF and NSCLC in the future." (PMID 34702952, 2021). "Periostin has been linked to EMT induction in cancer cells when overexpressed." (PMID 34200480, 2021). "Moreover, in animal models, POSTN suppression was reported to improve the progression of cancer variants." (PMID 33919736, 2021). "Another study also supports that Osteopontin induces mesenchymal stem cells in the tumor microenvironment (TME) to differentiate into cancer-associated fibroblasts (CAFs), which promotes cancer development and can be stimulated to release periostin in the metastatic microenvironment." (PMID 32260363, 2020). "Additionally, there was an association between periostin expression in cancer cells and the presence of calcifications." (PMID 31936272, 2020). "Notably, periostin expression has also been shown to be associated with chemo-resistance in pancreatic and other cancers." (PMID 32195182, 2020). "The ability to detect the cancer-specific bisecting glycoform on periostin would be a superior biomarker for diagnostic applications and may lead to the development of new therapeutic approaches." (PMID 30911061, 2019). "As we will see in detail, POSTN expression is frequently overexpressed by the stromal component of solid tumors and is frequently associated to poor prognosis and metastasis in many cancers." (PMID 29946533, 2018). "Furthermore, chemotherapy upregulated cancer-specific variants of periostin and application of a blocking antibody specifically targeting those variants overcame chemoresistance and halted disease progression without toxicity." (PMID 29507310, 2018). "Recently, periostin expression has been implicated in various types of cancer, including PDAC." (PMID 29163770, 2017).
cancer (continued). "The protein encoded by POSTN has been reported to function in cancer stem cell." (PMID 29348878, 2017). "Given its dual role as a component of matrix stiffening and pro-invasive signalling, many recent reports have unsurprisingly linked periostin to cancer promotion and poor survival suggesting that it is also a good potential therapeutic target for suppressing cancer development." (PMID 27515461, 2016). "The fact that periostin has been implicated in many of the same processes suggests that the PI3K–Akt pathway may act as a node for periostin signalling in cancer." (PMID 25345775, 2015). "Therefore, POSTN inhibition can be proposed to target mesenchymal transition and cancer cell invasion, two major causes of GBM aggressiveness and failure of current therapy." (PMID 21998659, 2011). "The expression of periostin is stimulated in pathological states by a wide range of factors, including interleukin 4 and 13, transforming growth factor beta, angiotensin 2, bone morphogenic protein 2, connective tissue growth factor 2, mechanical stretch, and several cancer-associated mediators." (PMID 40053143, 2025). "Furthermore, we showed that POSTN+ CAFs associated with cancer progression and poor clinical outcomes and may provide new insights on the treatment of NSCLC." (PMID 38115703, 2023). "Also, elevated periostin levels were detected in the serum of some cancer patients, suggesting that it could be a useful diagnostic and prognostic biomarker." (PMID 36224629, 2022). "Importantly, we identified a previously unreported CAF subpopulation characterized by high expression of POSTN, a gene encoding a protein that supports the adhesion and migration of epithelial cells, in addition to promoting cancer stem cell maintenance and metastasis." (PMID 34976204, 2022). "To examine the effect on cancer cells of a loss of the periostin secreted by fibroblasts, we examined whether adding OC-20, a neutralizing antibody of periostin, to iCM would cancel the effects of periostin on NSCLC cells." (PMID 34702952, 2021). "As current research continues to focus on the study of the mechanism and prognostic significance of periostin, these data may contribute to refine our knowledge of periostin as a cancer-associated glycoprotein and lead to a better understanding its role in cancer biology." (PMID 32719746, 2020). "In addition to cancer cells, POSTN is also present in cancer-associated fibroblasts (CAFs)." (PMID 29946533, 2018). "Therefore, we investigated whether integrin β1/AKT/GSK-3β/β-catenin/TCF4/Nanog signal pathway was implicated in POSTN promoting cancer stem phenotypes of heat-exposed residual HCC cells." (PMID 28526827, 2017). "Thus, POSTN contributes to fibrillogenesis during normal tissue development, and tissue remodeling associated with various diseases, wound repair, inflammation and cancer." (PMID 29100496, 2017). "While overall expression was low, possibly due to the age of these specimens, we noted a predilection for POSTN expression at cancer cell-normal tissue interfaces." (PMID 39511408, 2025). "Periostin and PTPRK have previously been reported to be associated with drug resistance in cancer and cancer stem cells." (PMID 40518514, 2025). "The Smad2/3-positive cancer cell group (n = 144) was significantly correlated with a high relapse rate (p = 0.032), a high advanced stage (p = 0.049), and periostin positivity (p < 0.001)." (PMID 39941916, 2025). "Periostin–integrin binding has been shown to play a critical role in promoting cancer cell migration and invasion, with the FAK/ERK pathway serving as a central mediator of these effects." (PMID 39941916, 2025). "Periostin is a well-studied protein that has been shown to interact with extracellular matrix proteins and plays a key role in tissue regeneration and cancer progression, promoting proliferation, invasion, and anti-apoptotic signaling 46,64–66." (PMID 36711927, 2025).
cancer (continued). "We found upregulation of factors such as FGF2, POSTN, and LTBP4 in classic morphology tumors, all of which are closely linked to activated cancer-associated fibroblasts (CAFs) and ECM remodeling." (PMID 41155518, 2025). "It has been suggested that periostin secreted by stromal cells interacts with integrins (such as αvβ3 or αvβ5) on the surface of cancer cells to stimulate the FAK/ERK pathway, thereby increasing the secretion of TGFβ." (PMID 39941916, 2025). "There are two possible ways in which POSTN promotes HCC cell proliferation: On the one hand, POSTN produced by cancer cells directly acts on themselves through autocrine to promote proliferation." (PMID 41018265, 2025). "After recognizing the pivotal role of POSTN as a mediator in fibroblast-cancer cell communication, we validated the function of POSTN in promoting EMT in PDAC cells." (PMID 40520021, 2025). "Beyond its role in forming a physical barrier that impairs drug delivery, periostin has been demonstrated to protect cancer cells from chemotherapy and radiotherapy through paracrine signaling and activation of the AKT and MAPK pathways." (PMID 40437741, 2025). "Of these cancer-promoting markers, we observed increases in POSTN gene expression after 8 days of PFOA treatment." (PMID 41154660, 2025). "POSTN signaling is mediated by integrin receptors, and integrins α5β1, αVβ3, and αVβ5 function as receptors for POSTN in other human cancer types." (PMID 39511408, 2025). "Recent studies have identified periostin as a key factor in CAF-mediated ESCC progression, where periostin in CAFs enhances both cancer and stromal cell migration." (PMID 41476608, 2025). "T1 and T2 clusters exhibited similar marker genes, including POSTN, COMP, and THBS2, which are markers associated with cancer-associated fibroblasts, showing heightened expression." (PMID 39670859, 2025). "Plasma periostin levels were elevated in multiple types of cancer patients, including colon, NSCLC and HCC patients, and were correlated with poor survival." (PMID 38279150, 2024). "POSTN-positive stromal cells were recently demonstrated to guide lymphovascular invasion by cancer cells in BC." (PMID 39335478, 2024). "Overexpression of POSTN is evident in various types of human cancers, including lung cancer and cancer cell lines." (PMID 39329988, 2024). "To evaluate the inhibition effect of POSTN exon 17 in cancer, we emoloyed exon skipping into cancer cells." (PMID 39272982, 2024). "Subsequent ISH showed that pathological POSTN exon 17 was expressed not only in the cancer cells but also in the stroma surrounding cancer." (PMID 39272982, 2024). "Pre-CAFs exhibited a high expression of genes like PDGFRA, POSTN, BMP2, BMP5, CEBPB, and BICC1, associated with the serrated pathway of CRC and cancer progression." (PMID 39456726, 2024). "We previously identified periostin as a macrophage-induced HStC-derived factor that drives cancer cell proliferation." (PMID 38678021, 2024). "In cancer, POSTN contributes to EMT by organizing the resident structural proteins into an integral network." (PMID 39329988, 2024). "POSTN is required for the maintenance of cancer stem cells and its function can be inhibited to prevent metastasis." (PMID 39272982, 2024). "After verifying POSTN splicing variant expression, we planted to evaluate the effect of the inhibition of pathological POSTN with exon 17 in stroma and cancer separately." (PMID 39272982, 2024). "Past reports have also suggested that POSTN with exon 21 has a clear role in supporting the development of cancer." (PMID 39195230, 2024). "POSTN is expressed at extremely low levels in healthy tissues but is overexpressed in cancers, including GBM." (PMID 39227950, 2024). "It has been shown that POSTN, being a factor stimulating angiogenesis, has the ability to bind to integrin receptors (αvβ3, αvβ5, α6β4) located on the surface of cancer cells." (PMID 39272978, 2024).
cancer (continued). "To evaluate the differential expression of POSTN in cancer tissues at mRNA levels, we first analyzed the GEPIA2 program." (PMID 38389400, 2024). "Many reports draw attention to the role of POSTN as one of the key factors that can significantly affect the process of new blood-vessel formation, especially in the context of cancer." (PMID 39272978, 2024). "Periostin also contributes to cancer stem cell or mesenchymal stem cell attributes in the colorectal mucosa and helps to sustain stemness, which correlates with poor chemotherapy response." (PMID 38532103, 2024). "Several studies have demonstrated the binding of αvβ3 and αvβ5 integrins to Periostin in various cell types, including osteoblasts and cancer cells, leading to the activation of signalling pathways such as the Focal Adhesion Kinase (FAK) pathway." (PMID 38892298, 2024). "The aim of this study was to analyze the correlation of POSTN expression (in cancer cells and CAFs) with pro-angiogenic factors (CD31, CD34, CD105, and VEGF-A) in patients with NSCLC." (PMID 39272978, 2024). "In this study, we evaluated the importance of inhibiting stromal or cancer pathological POSTN with exon 17 separately." (PMID 39272982, 2024). "Periostin (Pn), one of the ECM proteins secreted mainly by CAFs, is known to be associated to cancer progression, metastasis and chemoresistance in a variety of malignancies including PDAC." (PMID 39684914, 2024). "The fused cancer cells demonstrated more intense mesenchymal cell features, i.e., higher expression of POSTN, GDF11, IGFBP5 and CXCL11, and down-regulation of DAPK1, as well as greater proliferation and viability." (PMID 39120301, 2024). "To investigate the correlation between POSTN expression and clinical characteristics, we analyzed data from the Kaplan–Meier plotter database and clinical data sourced from the cancer genome atlas (TCGA)." (PMID 38389400, 2024). "They reported that in the analyzed material with a high POSTN expression in cancer cells, higher vascular density was found, which suggests the role of the POSTN glycoprotein in angiogenesis." (PMID 39272978, 2024). "The purpose of this study is to elucidate the effect of pathological POSTN with exon 17 inhibition in stroma or cancer separately." (PMID 39272982, 2024). "Qin and colleagues discovered that Periostin exhibits a high concentration in the ECM of cancerous tissue, predominantly originating from cancer‐associated fibroblasts." (PMID 38946720, 2024). "The results show that the pathological POSTN with exon 17 from both fibroblasts and cancer significantly increased IL-6 and IL-8 in each other’s cells." (PMID 39272982, 2024). "POSTN has four major splicing variants (PN1–4), which are primarily expressed in fibroblasts and cancer." (PMID 39272982, 2024). "Taken together, this proves for the first time the importance of inhibiting pathological POSTN with exon 17 in both stromal and cancer for the mice TNBC model separately." (PMID 39272982, 2024). "This particular type of CAFs, known as POSTN+ CAFs, play a significant role in shaping the environment for “cancer-embryo” reprogramming." (PMID 39524442, 2024). "Regarding malignancy, elevated POSTN levels have been detected in the serum of patients with cancer, suggesting its usefulness as a biomarker for diagnosis, metastasis, and prognosis." (PMID 38020106, 2023). "Aberrantly expressed POSTN by stromal cells modulates intracellular signaling pathways of cancer cells and accelerates many types of malignant phenotypes including migration, invasion, and EMT." (PMID 36765564, 2023). "In various cancers, periostin has been shown to induce signaling cascades including PI3K-Akt through attaching to αvβ3 and αvβ5 integrins." (PMID 37092398, 2023). "We also showed enhanced cancer stemness and lipid production when periostin levels are elevated in the culture media, mimicking the TME." (PMID 38049490, 2023).
cancer (continued). "Conversely, the introduction of Periostin boosted cancer cell proliferation in vitro which is consistent with its well-established role in cell proliferation." (PMID 38139195, 2023). "In various cancers, the elevated POSTN expression is observed and is involved in malignant behaviors." (PMID 36691359, 2023). "POSTN+ CAF-derived POSTN promotes the cancer stem cell (CSC) phenotype of HNSCC by activating protein tyrosine kinase 7 (PTK7)-Wnt/β-Catenin signaling through binding to PTK7 in cancer cells." (PMID 37143134, 2023). "Periostin is an extracellular matrix protein involved in various pathophysiological processes, including cell proliferation and cancer pathogenesis." (PMID 37353600, 2023). "A novel cancer cell‐derived POSTN isoform (Iso5) was specifically identified in HNSCC cells and synergistically enhanced invasion with a common isoform (Iso3)." (PMID 36691359, 2023). "The results showed that decreased extracellular collagen levels after periostin suppression; reduced levels of collagen increased the cytotoxic activity of NK cells and cell death increased in both cancer cells and PSCs." (PMID 36830807, 2023). "Periostin is a matricellular protein belonging to a family of proteins which are shown to regulate key features of cancer behavior such as invasion, proliferation, remodeling, and dissemination." (PMID 36671668, 2023). "Co‐labeling with anti‐SPARC and anti‐periostin antibodies showed that SPARC (in green) partially co‐localized with periostin (in red) in CAFs at the cancer cell‐stromal interface." (PMID 36346290, 2023). "In contrast to its roles in the normal physiological process, aberrant expression of periostin is found in the cancers in skin, lung, prostate, bladder, and pancreases, as well as melanoma and cutaneous T cell lymphoma." (PMID 36598904, 2023). "Cancer cells showing resistance to various drugs including cisplatin and 5-fluorouracil (5-FU) also show increased periostin expression." (PMID 37092398, 2023). "Periostin is produced by adipocytes or fibroblasts and is secreted into the cancer extracellular matrix." (PMID 38049490, 2023). "OPN, TnC, and POSTN significantly stimulated cell motility and the cancer-stem-cell-like phenotype in HuCCT-1 (human iCCA cell line)." (PMID 36902188, 2023). "POSTN is overexpressed in a variety of cancer CAFs and promotes various biological processes, including invasion and metastasis, by binding to appropriate integrin receptors or affecting the microenvironment." (PMID 37143134, 2023). "A more comprehensive in vivo study of periostin function in recurrent cancer development is warranted in the future." (PMID 38049490, 2023). "Recent data suggest that periostin can be used as a prognostic marker in various cancers including pancreatic, ovarian, and esophageal cancers." (PMID 37092398, 2023). "Immunohistochemistry staining confirmed that periostin protein levels were elevated in rOC relative to the matched pOC and exhibited higher levels in the stromal tissues than in the cancer cells." (PMID 38049490, 2023). "Periostin activates Akt phosphorylation in cancers including epithelial and ovarian cancer and carcinoma and this results in resistance, especially to paclitaxel." (PMID 37092398, 2023). "SPARC induces cancer migration and homing through the αVβ5 integrin, whereas periostin and IL-6 promote prostate tumor survival." (PMID 36900309, 2023). "Prior reports suggested that cancer stromal tissues express high levels of periostin and that this is related to poorer prognosis." (PMID 38049490, 2023). "On the other hand, metastatic colonization can be achieved by stromal periostin via the interaction between cancer stem cells and their metastatic niche." (PMID 36691359, 2023). "Various reports show that periostin is aberrantly expressed in pathological conditions such as arthritis, cancers, and fibrosis." (PMID 37092398, 2023).